NLRP3 (NLR family pyrin domain containing 3)
Diseases named in the same sentence as NLRP3 in open-access papers (continued):
Sharing a sentence is not in itself a finding about the gene and the disease.
infection (continued). "Collectively, these data indicate that the protective mechanism of PSPAs against infection is to promote mitophagy to ameliorate KP-induced mitochondrial dysfunction and then inhibit the formation of NLRP3 inflammasome and pyroptosis." (PMID 34768852, 2021). "On the other hand, robust and NLRP3-dependent responses were observed to the agonists nigericin, ATP, and R837, which mimic the presence of infection or tissue damage." (PMID 33440601, 2021). "One hundred percent of both the wild-type and Nlrp3−/− mice infected with 1×105 CFUs of the F. tularensis LVS succumbed to infection." (PMID 34690967, 2021). "The levels of IL-2, G-CSF, IFN-γ, and RANTES were significantly higher in the Nlrp3−/− mice than the wild-type mice on day 7 post-infection." (PMID 34690967, 2021). "On day 22, we found that the NLRP3 levels of the laser (0.48 ± 0.06) (P = 0.004) and infection (0.55 ± 0.05) (P = 0.004) groups were both higher than that of the HC group." (PMID 34908455, 2021). "At days 1 and 3 post-infection, WT mice had significantly higher levels of brain IL-18 than NLRP3-/- and ASC-/- mice, demonstrating that ASC-dependent inflammasomes are also essential for IL-18 production during HSE." (PMID 33524073, 2021). "By recognizing pathological infections and endogenous danger signals, NLRP3 inflammasome can trigger immune responses and inflammatory responses." (PMID 34707607, 2021). "After infection, the NLRP3-specific inflammasome is stimulated by DENV through inflammasome activation." (PMID 34394108, 2021). "The inflammasomes, and more specifically the NLRP3 inflammasome, are crucial components of the innate immune system and are usually activated in response to infection or tissue damage." (PMID 34209586, 2021). "Many chronic diseases can be initiated or aggravated by signals activating the NLRP3 inflammasome, including DAMPs derived from tissue and cell damage and PAMPs derived from infections." (PMID 33534121, 2021). "The results demonstrated that NLRP3 assembly plays a crucial role in SFTSV infection induced IL-1β secretion." (PMID 33708197, 2021). "After influenza virus strain A/Puerto Rico/8/34 (PR8) infection, NLRP3 was found to be important for the migration of leukocytes into the lungs and to protect the host from infection." (PMID 34531860, 2021). "In animals with prior infection, their heat tolerance was severely impaired and NLRP3 inflammasome induced neuroinflammation was detected." (PMID 34092247, 2021). "The sensor NLRP3 protein can be triggered by PAMPs, DAMPs, and a range of diverse external stimuli such as infection and injury." (PMID 34439904, 2021). "To date, NLRP3-mediated inflammasome is most studied, due to its crucial involvement in various infection- and non-infection-triggered inflammation." (PMID 34009097, 2021). "While none of the inflammasomes found in our study had a role in protection from the induced cytokine storm in ocular tissues, NLRP3 inflammasome has been shown to have a protective role during infection." (PMID 35046947, 2021). "This was also validated by real time PCR showing a mean Ct-value of 27.3 (Renal fibroblasts), 31.5 (A498) and 35.1 (HK-2) for NLRP3 after CFT073 infection at MOI 1 for 4 h." (PMID 34944029, 2021). "The production of NLRP3 inflammasome-mediated inflammatory cytokines and pyroptotic cell death are essential for fighting numerous infections and cancer." (PMID 34829842, 2021). "We next investigated if the detrimental effect of Nlrp3 in response to primary infection with F. tularensis is dependent on its role as an inflammasome activator." (PMID 34690967, 2021). "L. Hou found that NLRP3 activated by various dangerous states (including infection and metabolic abnormalities) induced macrophage pyroptosis to release inflammatory mediators, resulting in ALI." (PMID 34093568, 2021). "The positive cell rate of NLRP3 and caspase-1 in the three infection groups increased first and then decreased during the period from 0.5 to 9 h post-infection." (PMID 33678162, 2021).
infection (continued). "It is well known that the innate immune response and activation of the Nlrp3 inflammasome are important defense mechanisms during the first days of infection, until acquired immunity responds with the production of antibodies." (PMID 32691370, 2021). "This review provides the most updated information that caspase 8 skews the NLRP3 inflammasome activation in PANoptosis during pathogen infection." (PMID 34768828, 2021). "Significantly higher levels of IL-2, IFN-γ, and RANTES were observed in Nlrp3−/− mice on day 7 post-infection." (PMID 34690967, 2021). "The stimuli that activate the NLRP3 inflammasome range from pathogen infection and endogenous danger signals to environmental irritants." (PMID 33534121, 2021). "Generally, these results confirm that the activation of the NLRP3 inflammasome was accumulated when infection time and dose were increased within a certain range." (PMID 34869071, 2021). "NLRP3 is a protective PRR against infections by highly diverse agents including viruses, bacteria, fungi and parasites." (PMID 34615873, 2021). "Previous observations that Nlrp3 drives Th2 polarization by regulating transcription led us to investigate differences in gene expression profiles between wild-type and Nlrp3−/− mice in response to F. tularensis LVS infection." (PMID 34690967, 2021). "The differences in NLRP3 inflammasome following infection with different Chlamydia species have been documented, suggesting that IL-10−/− has a specific effect on NLRP3-mediated apoptosis." (PMID 34093535, 2021). "The transcript levels of Clr, DEC-205 were significantly higher in the Nlrp3−/− compared to the wild-type mice on day 7 post-infection." (PMID 34690967, 2021). "The infected Nlrp3−/− mice lost body weight for up to 6days post-infection, and those that survived regained their initial body weight." (PMID 34690967, 2021). "The NLRP3 inflammasome is activated by cell infection or stress and plays a vital role in the expression of proinflammatory mediators." (PMID 34356813, 2021). "Clones of DH82 cells lacking the caspase-1/-4 gene showed similar responses (cell death and IL-1β production) to WT DH82 cells after infection with S. Typhimurium, or stimulation with NLRP3-activating concentrations of nigericin." (PMID 34433041, 2021). "The NLRP3 inflammasome is a vital component of sterile- and infection-triggered inflammation as well as of the immune responses to various diseases." (PMID 33663554, 2021). "Taken together, these results demonstrate that during infection with the ΔpknF mutant, XO plays an important role in the generation of ROS that in turn is responsible for activation of NLRP3 inflammasome and increased production of IL-1β." (PMID 34324582, 2021). "One hundred percent of Nlrp3−/− mice survived the infection dose of 0.6×104 CFUs, while only 33% (2/6 mice) wild-type mice survived this infection dose." (PMID 34690967, 2021). "The NLR family pyrin domain-containing 3 (NLRP3) inflammasome plays an important anti-infection role." (PMID 34093535, 2021). "On day 3 post-infection, wild-type and Nlrp3−/− mice had similar bacterial burdens in their lungs, livers, while the Nlrp3−/− mice harbored significantly fewer bacteria in their spleens." (PMID 34690967, 2021). "Candidalysin is both a central trigger for NLRP3 inflammasome-dependent caspase-1 activation via K+ efflux and a key driver of inflammasome-independent cytolysis of macrophages upon infection with C. albicans." (PMID 34795266, 2021). "Nearly equal numbers of bacteria were recovered from wild-type and Nlrp3−/− macrophages at 4h post-infection, indicating similar numbers of bacteria entered the cells." (PMID 34690967, 2021). "The NLRP3 inflammasome is a key constituent of the innate immune system and has a crucial role in infection recognition and promoter of autoimmune responses." (PMID 34959607, 2021).
infection (continued). "DDX3X primarily engaged assembly of SGs upon IAV–ΔNS1 infection and promoted NLRP3 inflammasome activation in response to NS1-expressing IAV, suggesting a mutually exclusive behavior of these host innate responses." (PMID 33766561, 2021). "HPI+/HPI−-infection was accompanied by upregulated expression levels of NLRP3, ASC, caspase-1, IL-1β, IL-18 and GSDMD, with significantly higher levels detected in the HPI+ group compared to those in the HPI− group (P < 0.01 or P < 0.05)." (PMID 33678162, 2021). "Previous studies have clearly shown that the NLRP3 inflammasome is critical for promoting IL-1β activity by inducing excessive neutrophil recruitment to the site of infection in the skin." (PMID 34011393, 2021). "To examine how development of NLRP3 inflammasomes was affected by infection with P. gingivalis or S. mitis, we measured the expression of NLRP3, CASP1, and ASC at 1, 2, 6, and 24 h (MOI = 50) time points." (PMID 32903638, 2020). "We next assessed the transcriptional effect of infection on the TLR-NF-κB signaling pathway given its essential role of NLRP3 priming." (PMID 32582184, 2020). "H. pylori/Nigericin-treated cells also exhibited a similar decrease in mature IL-1β secretion at later periods of infection due to both decreased NLRP3 expression and inflammasome activation." (PMID 32230726, 2020). "Mtb triggers NLRP3 inflammasome in mice, as well as in some in-vitro models of human macrophages; however, the multiplicity of infection (MOI) implied is always high (1–10 or more) compared to what expected during natural infection (<<1)." (PMID 33193317, 2020). "The phagosomes acidified to pH <4 after 4 h post-infection in parental J774A.1 cells, whereas the phagosomes acidified to pH >4 in V. vulnificus-infected NLRP3 KO cell." (PMID 33117816, 2020). "One of the fundamental reactions of the innate immune responses to pathogen infection is the release of pro-inflammatory cytokines, including IL-1β, processed by the NLRP3 inflammasome." (PMID 32187211, 2020). "In the context of infection, this means that the NLRP3 pathway needs to respond to dangerous microbial colonisation (i.e. infection), but there should be limited activation in response to benign, harmless colonisation." (PMID 32750090, 2020). "After overexpression of NLRP3 and infection with GM, IL-1β expression increased from 107.5 pg/mL to 169.3 pg/mL, and after inhibition of NLRP3 with Si-RNA, the expression of IL-1β decreased from 152.8 pg/mL to 87.0 pg/mL." (PMID 32293543, 2020). "As two types of endogenous dominant-negative proteins, both COPs (CARD-only proteins) and POPs (PYD-only proteins) decrease the activity of the NLRP3 inflammasome in response to tissue injury and pathogen infection." (PMID 32973739, 2020). "Infection with B. thailandensis triggered caspase-1 mediated release of IL-1β and IL-18 and caspase-11 induced activation of the NLRP3 inflammasome leading to death of infected lung epithelial cells by pyroptosis in mice." (PMID 33329561, 2020). "A key microbe recognised by NLRP3 is the human yeast commensal and pathogen Candida albicans, which is responsible for mucosal and invasive infections." (PMID 32750090, 2020). "After infection of T. gondii, mGbp2B (also named Gbp1) can activate inflammasome complex signaling cascades, which leads to Nlrp1, Nlrp3, Nlrp4, and pro-caspase-1 degradation resulting in converting the cell death type from pyroptosis to apoptosis." (PMID 32731337, 2020). "The mechanisms of NLRP3 inflammasome activation required for IL-1β generation during infection by Leishmania have been recently elucidated." (PMID 33061823, 2020). "It has even been suggested that in vitro infection of human neutrophils leads to evasion of NLRP3 activation and IL-1β secretion." (PMID 32753607, 2020).
infection (continued). "Flaviviruses, including the West Nile virus, swine fever virus (CSFV), Japanese encephalitis virus, and hepatitis C virus, have been shown to assemble the NLRP3 inflammasome and promote IL-1β production during infection." (PMID 32210961, 2020). "A recent study has demonstrated that Brucella ligands activate NLRP3 inflammasomes, leading to infection control." (PMID 33414782, 2020). "It has been shown that activation of NLRP3 by SARS-CoV is a mechanism triggering the inflammatory response to this infection." (PMID 33264297, 2020). "We have noticed that the level of NLRP3 mRNA expression was also decreased when treated with PA infection." (PMID 33489931, 2020). "As we previously demonstrated, Fn U112 infection of NLRP3 inflammasome-reconstituted HEK293T cells elicited robust IL-1β production and cells lacking NLRP3, or expressing NLRP2, yielded IL-1β levels comparable to uninfected controls." (PMID 32983094, 2020). "Infection of IFNγ‐primed human THP1 cells with L. monocytogenes strain 10403S results in enhanced NLRP3 activation assisted by the IFNγ‐inducible GBP5." (PMID 32185892, 2020). "ASC specs were found in the plasma of HIV positive patients, and infection with HIV stimulated the NLRP3 inflammasome in monocytes as well as production of caspase-1, IL-1β and IL-18 in brain microglial cells." (PMID 32066471, 2020). "The body weights of infected NLRP3-/- mice decreased continuously until died, while the body weights of infected WT mice gradually decreased until 7 days post-infection and then gradually increased." (PMID 32187211, 2020). "There are several reports showing that H. pylori activated the NLRP3 inflammasome during mouse infection." (PMID 32230726, 2020). "Like H37Rv which also activates inflammasomes, the survival of the inflammasome-activating isolate 411 was markedly reduced in Nlrp3−/− cells at 24 h post-infection." (PMID 32111888, 2020). "It has been demonstrated that severe infection injury can promote the activation of NLRC4 as well as NLRP3 inflammasome, regulate the activation of Caspase-1, and eventually lead to inflammatory injury." (PMID 33489931, 2020). "NLRP3-deficient and ASC-deficient cell infection resulted in drastic loss of lytic cell death, consistent with their central role in the inflammasome and caspase-1 activation." (PMID 32854254, 2020). "The response of NLRP332 to L. monocytogenes (Lm) infection and stimulation with the sterile NLRP3 inflammasome agonists nigericin and H2O2 was also examined." (PMID 32983094, 2020). "To investigate the infection status of these cells, we infected control null, ASC-deficient, and NLRP3-deficent cells with mKate2-expressing RSV (mKate-2-RSV)." (PMID 32854254, 2020). "Activation of the immune regulator NLRP3 inflammasome by microbial pathogens has been shown to play both protective and destructive roles in infection, underscoring the importance of tight control over NLRP3-driven inflammation to ensure host health." (PMID 32750090, 2020). "Remarkably, infection of Nlrp3-/- BMDMs resulted in a delayed cell death phenotype, similar to the phenotype observed when inflammasome inhibitors were added to WT BMDMs." (PMID 32013758, 2020). "From a clinical viewpoint, our study also provides valuable insights identifying the NLRP3-IL-1β-IL-1R1 axis as potential targets for developing new drug therapies for preventing severe infection-elicited chronic inflammation and neurodegeneration." (PMID 32070376, 2020). "Together, our data demonstrate that Mtb induces potassium efflux-driven activation of the canonical NLRP3 inflammasome upon infection of human monocytes and macrophages, followed by GSDMD-dependent pyroptotic cell death with release of IL-1β." (PMID 32385301, 2020). "NLRP3 promotes the secretion of IL-33, IL-18, and IL-1β, which are very important molecules that control pathological infections." (PMID 32973739, 2020).
infection (continued). "NLRP3 is the most commonly studied protein in the inflammasomes and activated by infection, tissue lesion and oxidative stress." (PMID 33614540, 2020). "NLRP3 deficiency mice are more susceptibility to HSV-1 infection, exhibit early onset of death upon infection, represses IL-1β secretion, and elicits robust inflammatory responses in the tissues." (PMID 32187211, 2020). "Similar to TLRs, the NLRP3 inflammasome has also been shown to play a critical role in innate immune responses to injury and infection." (PMID 32508525, 2020). "For the case of Toxoplasma, inflammasome components NLRP1 and NLRP3 respond to infection resulting in IL-1β and IL-18 release, in turn promoting resistance to infection." (PMID 33505924, 2020). "THP1 monocytes were treated with caspase-1 inhibitor VX-765 (10 μM) 15 min before LPS treatment or infection with H. pylori, which followed Nigericin-mediated NLRP3 inflammasome activation." (PMID 32230726, 2020). "Infection of monocytes with S. Typhimurium activates the NLRP3 inflammasome, whereas in macrophages both NLRP3 and NLRC4 are activated." (PMID 32185892, 2020). "A second group of PAMs were then treated with pig-matched cell culture supernatants from these NLRP3 inflammasome inhibited or NLRP3 inflammasome activated PAMs prior to infection with either VR-2332 or Ingelvac MLV." (PMID 33198300, 2020). "Sex, age, smoking, current infection, BMI, and single nucleotide polymorphism in the inflammasome regulating genes CARD8 (C10X) and NLRP3 (Q705K) were included as covariates." (PMID 32256196, 2020). "In contrast, activation of the NLRP3 inflammasome and production of IL-1β led to an increase in the pathology of murine infection by L. braziliensis." (PMID 33192178, 2020). "Salmonella Enteritidis (SE) is one of the major foodborne zoonotic pathogens of worldwide importance which can induce activation of NLRC4 and NLRP3 inflammasomes during infection." (PMID 32723297, 2020). "After infection with C. albicans, the first wave of macrophage death is driven by activation of NLRP3 inflammasome-dependent pyroptosis and has been termed “Phase I death”." (PMID 32750090, 2020). "A recent study showed that the outer membrane protein 34 (Omp34) of Acinetobacter baumannii, a Gram-negative opportunistic pathogen, triggers mtROS generation, leading to the hyper-activation of NLRP3 inflammasome and pyroptosis during infection." (PMID 32922385, 2020). "Future studies, especially those considering the complex interplay of human genetics, immuno-suppressive status, and age with pneumococcal colonization are needed to better understand the role of NLRP3 inflammasome in such infections." (PMID 33424869, 2020). "Based on the pneumococcal serotypes used for the infection, the NLRP3-dependent IL-1β secretion by human cells varies." (PMID 33424869, 2020). "Here, we show that CaSR upregulation after infection in TM in a rat model of UPEC induces the activation of the NLRP3 inflammasome pathway and thereby enhances IL-1β secretion and reduces the testosterone level in the blood." (PMID 33193351, 2020). "The number of engulfed bacteria in wild-type and NLRP3 knockout J774A.1 macrophages was determined by the CFU assay after 15 min of infection." (PMID 32582195, 2020). "Histology also demonstrates severely attenuated inflammatory response to infection in Nlrp3–/– mice." (PMID 32508813, 2020). "Many of the brain’s immune functions are carried out by microglia, which in their resting state survey the environment for infection or tissue damage with supressed NLRP3 inflammasome functions." (PMID 32883606, 2020). "The residual caspase-1/11, ASC-dependent and NLRP3/AIM2-independent maturation of IL-1β in response to infection with H37Rv and isolate 411 suggests the involvement of an additional inflammasome sensor in detecting these bacteria." (PMID 32111888, 2020). "NLRP3 inflammasome is a multiprotein complex formed in the cytoplasm during infection to cope with cell damage." (PMID 32118052, 2019).